HAND2 (heart and neural crest derivatives expressed 2)
Description:
Essential for cardiac morphogenesis, particularly for the formation of the right ventricle and of the aortic arch arteries. Required for vascular development and regulation of angiogenesis, possibly through a VEGF signaling pathway. Also plays an important role in limb development, particularly in the establishment of anterior-posterior polarization, acting as an upstream regulator of sonic hedgehog (SHH) induction in the limb bud. Is involved in the development of branchial arches, which give rise to unique structures in the head and neck. Binds DNA on E-box consensus sequence 5'-CANNTG-3' (By similarity).
Synonyms: bHLHa26; dHAND; Thing2; Hed; DHAND2
Tractability: PROTAC: ubiquitination databases record sites on it.
Gene: Protein-coding gene on chromosome 4 (173,524,969 to 173,530,229, reverse strand). Ensembl gene ENSG00000164107.
Subcellular location: Nucleus
Subcellular location (Human Protein Atlas): Nucleoplasm; Vesicles
Pathways (Reactome):
Developmental Biology: Cardiogenesis
Gene expression (Transcription): Transcriptional regulation by RUNX2
Gene Ontology:
Molecular function: DNA-binding transcription activator activity, RNA polymerase II-specific; E-box binding; minor groove of adenine-thymine-rich DNA binding; protein binding; RNA polymerase II transcription regulatory region sequence-specific DNA binding; sequence-specific double-stranded DNA binding; DNA-binding transcription factor activity, RNA polymerase II-specific; RNA polymerase II-specific DNA-binding transcription factor binding; transcription cis-regulatory region binding; transcription coactivator binding; DNA-binding transcription factor activity; protein dimerization activity; protein homodimerization activity; sequence-specific DNA binding
Biological process: adult heart development; negative regulation of gene expression; positive regulation of cardiac muscle hypertrophy; positive regulation of ERK1 and ERK2 cascade; positive regulation of gene expression; positive regulation of p38MAPK cascade; positive regulation of transcription by RNA polymerase II; regulation of tissue remodeling; cardiac neural crest cell development involved in outflow tract morphogenesis; heart development; negative regulation of cardiac muscle cell apoptotic process; noradrenergic neuron differentiation; outflow tract morphogenesis; positive regulation of semaphorin-plexin signaling pathway; regulation of secondary heart field cardioblast proliferation; regulation of transcription by RNA polymerase II; thymus development; cardiac right ventricle formation; cellular response to retinoic acid; embryonic skeletal system development
Cellular component: chromatin; protein-containing complex; nucleus; transcription regulator complex
Genetic constraint (gnomAD): Loss-of-function variants: 2 observed, 10.47 expected, observed/expected ratio (o/e) 0.19, 90% interval 0.077 to 0.6. The synonymous counts are far from expectation, so gnomAD's model fits this gene poorly and the ratio says little. Missense variants: 268 observed, 256.19 expected, observed/expected ratio (o/e) 1.05, 90% interval 0.95 to 1.16. Synonymous variants: 157 observed, 110.67 expected, observed/expected ratio (o/e) 1.42, 90% interval 1.25 to 1.62.
Homologues: Orthologues: chimpanzee HAND2 (100% identical), dog HAND2 (100% identical), guinea pig HAND2 (100% identical), mouse Hand2 (100% identical), rat Hand2 (100% identical), pig HAND2 (99% identical), rabbit HAND2 (99% identical), tropical clawed frog hand2 (91% identical), macaque HAND2 (86% identical), zebrafish hand2 (82% identical), Drosophila melanogaster Hand (35% identical), Drosophila melanogaster twi (18% identical), and 3 more. Paralogues in human: HAND1 (54% identical), PTF1A (23% identical), TCF15 (23% identical), MSC (21% identical), SCX (21% identical), TWIST1 (21% identical), TWIST2 (21% identical), TCF21 (20% identical), TCF24 (19% identical), FERD3L (17% identical), TCF23 (17% identical), FIGLA (16% identical), and 1 more.
Diseases named in the same sentence as HAND2 in open-access papers:
HAND2 is named in the same sentence as 81 diseases in open-access papers, as found by Europe PMC text mining. Sharing a sentence is not in itself a finding about the gene and the disease. The quoted sentences say what the papers report.
neuroblastoma (28 papers, 2009 to 2025). Neuroblastoma (NB) is the most common solid, extracranial childhood tumor. "These NIPBL-bound MYCN peaks are highly enriched for motifs of core regulatory circuitry (CRC) transcription factors such as GATA3, PHOX2A, HAND1, and HAND2, which contribute to the maintenance of the neuroblastoma oncogenic cell identity." (PMID 40867243, 2025). "Altogether, these data provide evidence for recruitment by HAND2 of a RUNX1T1 repressor complex to help maintain an undifferentiated phenotype in MYCN-amplified neuroblastoma cells." (PMID 38992040, 2024). "HAND2 and DEIN expression is well correlated in neuroblastoma, HAND2 is highly expressed in neuroblastoma." (PMID 28350845, 2017). "Notably, this identified motifs with high similarity to the known binding motifs of several neuroblastoma core regulatory circuit transcription factor motifs including HAND2, GATA3 and PHOX2B." (PMID 36263020, 2022). "Thus, high levels of expression of either MYC or MYCN due to translocations hijacking next to the HAND2 super-enhancer produce neuroblastoma cells that are resistant to the effects of ATRA in inducing neuroblastoma cell differentiation." (PMID 34669465, 2021). "In addition, HAND2 is highly expressed in neuroblastoma (NB), a pediatric tumor arising from undifferentiated migrating sympathetic precursor cells that shows conspicuously divergent biological phenotypes ranging from spontaneous regression to rapid progression and metastasis." (PMID 19348682, 2009). "In contrast, NIPBL peaks that overlapped with MYCN binding were significantly enriched for motifs recognized by core regulatory circuitry (CRC) transcription factors critical to neuroblastoma cell identity, including GATA3, PHOX2A HAND1, and HAND2." (PMID 40867243, 2025). "A recent study has shown that several master regulators important in sympathoadrenal neural crest lineages, including PHOX2A/B, GATA2/3, HAND2, SOX4/11, and INSM112 form a CRC on which the neuroblastoma tumor cells are dependent for survival and growth." (PMID 38653778, 2024). "In this work, we show that RUNX1T1 forms part of a repressive complex in neuroblastoma cells acting on enhancer regions to support MYCN and HAND2 in driving neuroblast hyperplasia and eventual transformation." (PMID 38992040, 2024). "Markers of SA cells have been found to be highly expressed in neuroblastoma tumors and constitute the core regulatory circuitry in the adrenergic subtype of neuroblastoma, including PHOX2B, HAND2 and GATA310,11." (PMID 39367051, 2024). "In neuroblastoma, our analysis identified the transcription factors ISL1, HAND2, PHOX2B, PHOX2A, and MYCN as the top five targets critical for the survival of cell lines." (PMID 37297004, 2023). "GATA2 has been identified as a component of the transcriptional regulatory circuits involving super enhancers in neuroblastoma cells, which also includes GATA3, PHOX2A, PHOX2B, and HAND2." (PMID 36980710, 2023). "Cases in the other cluster also showed a high expression of CRC-related genes in neuroblastoma, such as GATA3 and HAND2." (PMID 33465163, 2021). "ChIP-seq for the PHOX2B, HAND2, and GATA3 TFs in the neuroblastoma CLB-GA cell line confirmed that binding regions for these three TFs corresponded to the H3K27ac peaks and SEs of the NOR identity." (PMID 34200747, 2021). "Genes known to be specifically expressed in neuroblastoma, such as HAND2, PHOX2B, and DBH, were homogeneously expressed across all samples, indicating that the proportion of mRNA derived from neuroblastoma cells was equally distributed between each sample." (PMID 34815394, 2021). "The adrenergic CRC consists of an interdependent autoregulatory network that includes HAND2, ISL1, PHOX2B, GATA3, ASCL1, and TBX2 and is essential to drive the expression of MYCN and to facilitate the growth and survival of MYCN-amplified neuroblastoma cells." (PMID 34669465, 2021).
neuroblastoma (continued). "ADRN-type neuroblastoma, showing sympathetic noradrenergic identity, was characterized by CRC modules formed by several transcription factors, such as HAND2, PHOX2B, and GATA3, leading to high expression of these genes." (PMID 33465163, 2021). "Gene expression levels for the adrenergic neuroblastoma CRC members—MYCN, HAND2, ISL1, PHOX2B, GATA3, ASCL1, and TBX2—were assayed by quantitative RT-PCR at 1, 3, and 6 days after treatment with 5 μM ATRA." (PMID 34669465, 2021). "Transcription factor ChIP-seq in MYCN-expressing cells confirmed that four of the enhancers (e1, e2, e4, and e5) were bound by each of three noradrenergic neuroblastoma core regulatory circuit transcription factors (PHOX2B, HAND2, GATA3)." (PMID 33199677, 2020). "Regulatory elements controlling ASCL1 expression are bound by LMO1, MYCN and the transcription factors GATA3, HAND2, PHOX2B, TBX2 and ISL1—all members of the adrenergic (ADRN) neuroblastoma core regulatory circuitry (CRC)." (PMID 31819055, 2019). "Neuroblastoma derives from embryonic neural crest cells, and in NB tumors that harbor amplification of the proto-oncogene MYCN, a transcriptional core regulatory circuitry (CRC) that includes MYCN, HAND2, ISL1, PHOX2B, GATA3, and TBX2 promotes tumorigenesis." (PMID 40766465, 2025). "Thus, ATRA initiates a change in cell state of neuroblastoma cells corresponding to a shift from the adrenergic CRC to a new retino-sympathetic CRC, which includes RARA, HAND2, ISL1, TBX2, TBX3, MEIS1, and SOX4." (PMID 34669465, 2021). "TBX2 (T-box 2 transcription factor) is a constituent of the NOR CRC in neuroblastoma cells, together with HAND2, GATA3, and PHOX2B." (PMID 34200747, 2021). "In addition, LMO1 occupancy was associated with enrichment of transcription factors that have previously been shown as members of the ADRN neuroblastoma CRC, including PHOX2B, HAND2, TBX2, and ISL15,19–21 (left)." (PMID 31819055, 2019). "This variant was found to be located in open chromatin regions identified in 29 ATAC‐seq and 5 H3K27ac ChIP‐seq experiments in various neuroblastoma cell lines, but also showed the highest enrichment of TF binding sites, including MYCN, LMO1, GATA3, HAND2, ISL1, PHOX2B, and TBX2." (PMID 40525640, 2025). "Indeed, MYCN, ISL1, HAND2, and PHOX2B, together with GATA3 and TBX2, comprise the core regulatory circuit, an autoregulatory transcriptional loop that maintains the malignant phenotype of MYCN-positive neuroblastoma." (PMID 37297004, 2023). "Finally, the interaction of MYCN with the transcription factor HAND2 (heart and neural crest derivatives-expressed protein 2), that permits MYCN chromosome accessibility and enhancer binding in neuroblastoma, was abolished by the Aurora-A inhibitor alisertib, disrupting tumour growth." (PMID 37414143, 2023). "HAND2, a key regulator for the development of the sympathetic nervous system, is located on chromosome 4q33 in a head-to-head orientation with DEIN, a recently identified novel gene with stage specific expression in primary neuroblastoma (NB)." (PMID 19348682, 2009). "To determine whether expression of HAND2 and DEIN is co-regulated in neuroblastoma, we performed Northern Blot analysis of 20 primary NB with HAND2- and DEIN-specific cDNA probes." (PMID 19348682, 2009).
congenital heart disease (10 papers, 2013 to 2023). A heart disease that is present at birth. "The effects on the phenotype are different for haploinsufficiency and for duplication of the HAND2 gene because only haploinsufficiency seems to be associated with congenital heart defects." (PMID 34946906, 2021). "Upstream regulators predicted to explain these effects included critical players such as Hand2 and miR-155, which have been associated with congenital heart disease and hypertrophic cardiomyopathy, respectively." (PMID 26555816, 2015). "This is the first report of a functionally significant HAND2 mutation in a patient with congenital heart disease." (PMID 25093829, 2014). "The synergistic activation between HAND2 and GATA4 TFs is causally linked to congenital heart diseases (CHD)." (PMID 37359008, 2023). "Note that our results do suggest a more prominent role for this interaction in both congenital heart disease and coronary diseases, but the fact that only one copy of the HAND2 gene is affected in this particular family makes it difficult to prove our hypothesis." (PMID 28469241, 2017).
endometrial cancer (10 papers, 2013 to 2025). Primary or metastatic malignant neoplasm involving the endometrium (mucous membrane that lines the endometrial cavity). "HAND2 gene hypermethylation and epigenetic silencing increase the risk of endometrial cancer development." (PMID 39621192, 2025). "In humans, age and a history of long-term progesterone/oestrogen imbalance (for which HAND2 methylation may potentially be the resulting final molecular surrogate) are the major risk factors for endometrial cancer." (PMID 24265601, 2013). "Although we have clearly shown that HAND2 methylation precedes the development of endometrial cancer, it is still unclear whether epigenetic silencing of HAND2 can be functionally linked to endometrial cancer development." (PMID 24265601, 2013). "Interestingly, age is also one of the main risk factors for endometrial cancer, hence it is plausible that age-associated HAND2 promoter methylation, if present in endometrial tissue, could be a contributing factor to endometrial cancer risk." (PMID 25692570, 2015). "Hypermethylated HAND2 and silencing is early molecular event in carcinogenesis, and provide as one biomarker for early detection of endometrial cancer." (PMID 35870943, 2022). "Epigenetic silencing of Hand2 has been reported in the development of endometrial cancer, which occurs in older women." (PMID 33258279, 2021). "We tested the effectiveness of the methylation status of four genes (BHLHE22, CDO1, TBX5, and HAND2) in endometrial cancer detection." (PMID 31779688, 2019). "This analysis identified HAND2 as the hub of the most highly ranked differential methylation hotspot in endometrial cancer." (PMID 24265601, 2013). "These and other findings identify HAND2 methylation as a common, key molecular alteration in endometrial cancer." (PMID 24265601, 2013). "Most importantly, HAND2 methylation was observed in over 90% of endometrial cancers, and thus represented, by far, the most frequent molecular alteration." (PMID 24265601, 2013). "Almost all endometrial cancer samples were strongly methylated and demonstrated a significant suppression of HAND2 mRNA (p<0.001)." (PMID 24265601, 2013). "A novel integrative epigenome-transcriptome-interactome analysis further revealed that HAND2 is the hub of the most highly ranked differential methylation hotspot in endometrial cancer." (PMID 24265601, 2013). "As HAND2 DNAme was a confirmed feature of endometrial cancer, we next sought to determine at which point during endometrial carcinogenesis HAND2 becomes aberrantly methylated." (PMID 24265601, 2013). "What we find here in CRC is similar to functions of HAND2 methylation in endometrial cancer." (PMID 35870943, 2022). "Also, a recent study on endometrial cancers showed HAND2 knock-out mice to get more pre-neoplastic alterations." (PMID 26485755, 2015). "We found that HAND2 methylation is able to predict response to progesterone and provides a sensitive test to correctly identify endometrial cancer patients amongst those women who present with postmenopausal bleeding through the DNAme analysis of endometrial secretions on high vaginal swabs." (PMID 24265601, 2013). "The researchers hypothesized, therefore, that epigenetic deregulation of HAND2 could be a key step in endometrial cancer development." (PMID 24265601, 2013). "We then sequenced the top-ranked gene—HAND2—and validated DNAme and RNA expression of this gene in an additional set of endometrial cancer and control tissues and, furthermore, compared HAND2 methylation to other common molecular alterations in endometrial cancer." (PMID 24265601, 2013).
endometrial cancer (continued). "Hence, to further investigate the functional role of HAND2 silencing in the earliest stages of endometrial cancer development, we studied changes in endometrial histology as a function of age in mice with a conditional knock-out of Hand2 in uterine tissue." (PMID 24265601, 2013). "Nevertheless, these results suggest that HAND2 methylation could potentially be used as a biomarker for the early detection of endometrial cancer and for predicting treatment response." (PMID 24265601, 2013). "The relevance of HAND2 in endometrial cancer is supported by several lines of published evidence." (PMID 24265601, 2013). "Consequently, our novel bioinformatic analysis led us to further investigate the role of HAND2 in endometrial cancer." (PMID 24265601, 2013). "This indicates that disruption of Hand2-mediated signalling solely in cells expressing the PR leads to morphological changes in the endometrium (i.e., CAH) associated with a very high likelihood of invasive endometrial cancer development." (PMID 24265601, 2013). "HAND2 methylation is a common and crucial molecular alteration in endometrial cancer that could potentially be employed as a biomarker for early detection of endometrial cancer and as a predictor of treatment response." (PMID 24265601, 2013). "Thus, we can conclude that HAND2 methylation is a common feature of endometrial cancer, largely independent of sequence variants, clinicopathological characteristics, and specific molecular endometrial cancer subgroups." (PMID 24265601, 2013). "In addition, the methylation pattern of the HAND2 gene was investigated in endometrial cancer, and it was revealed that the alterations in HAND2 DNA methylation commonly occur in endometrial cancer and could be utilized as a biomarker for early detection and a predictor of treatment response." (PMID 36443682, 2022). "Previously, the essential mediator of the early decidual response HAND2 was identified as a specific target of the GATA2 transcription factor, and hypermethylation of this gene is a common and crucial alteration in endometrial cancer." (PMID 28125717, 2017). "All EpiMods demonstrated strong enrichment for biological terms, with the HAND2 EpiMod itself highly enriched for other transcription factors (e.g., GATA4, HEY2, HOXD13, PHOX2A, HAND1), all of which were also hypermethylated in endometrial cancer." (PMID 24265601, 2013). "All these results indicate that HAND2 and the interaction neighbourhood of HAND2, including GATA4, HEYL, and PHOX2A, represent a core component that is epigenetically deregulated in endometrial cancer." (PMID 24265601, 2013). "Furthermore, the HAND2 EpiMod was a significantly functionally deregulated hotspot under the FEM analysis that incorporated independent gene expression data (12 normal and 79 cancerous endometrial samples—Set 2), with HAND2 demonstrating concordant underexpression in endometrial cancer." (PMID 24265601, 2013).